INF2 (inverted formin 2)
Diseases named in the same sentence as INF2 in open-access papers (continued):
Sharing a sentence is not in itself a finding about the gene and the disease.
renal disease (9 papers, 2014 to 2025). "This is the first report to identify an association between a familial autosomal dominant INF2 p.Arg214Cys mutation and rapidly progressive renal disease in an Asian family." (PMID 33541266, 2021). "Of particular note is a potential role of CaAR in kidney pathology, as INF2 is known to regulate actin dynamics in podocytes, and INF2 mutations are linked to hereditary kidney diseases." (PMID 27919320, 2016). "In contrast to wild-type human INF2, INF2 mutants associated with kidney disease fail to rescue the zINF2 morphant phenotype." (PMID 26086034, 2014). "It is plausible that, in addition to monogenic diseases caused by pathogenic INF2 mutations, normal INF2 could be aberrantly activated in conditions with altered intracellular Ca2+ levels, contributing to renal disease." (PMID 39586895, 2024). "DAAM2, which is expressed by podocytes, colocalizes and associates with INF2, suggesting the existence of crosstalk between the two formins that, given the link between INF2 and renal disease, may explain the renal damage caused by pathogenic DAAM2." (PMID 34685534, 2021). "Our patients with dual CMT–FSGS, both of whom have the proximal INF-2 DID variants, also had severe renal disease with early-onset SRNS (at the age of 10 years) and rapidly progressed to ESRD (by the age of 20 years)." (PMID 39857711, 2025). "CMT rarely co-occurs with the renal disorder of FSGS: a subtype, CMT-dominant intermediate (CMT-DIE, MIM 614455), is caused by mutations in the inverted formin-2 gene (INF2), encoding an actin assembly factor." (PMID 39857711, 2025). "In addition to those in the INF2 DID, numerous mutations are cataloged in public databases, with only a handful documented in patients with kidney disease." (PMID 39586895, 2024). "Mutations in seven formin genes (DIAPH1-3, DAAM2, FMN2, FHOD3 and INF2) are the genetic basis of various inherited human disorders, such as intellectual disability, renal disease, peripheral neuropathy, thrombocytopenia, primary ovarian insufficiency, hearing loss and cardiomyopathy." (PMID 39586895, 2024). "Thus, in a majority of the INF2 disorders, renal diseases are a common denominator in the clinical phenotype." (PMID 37491439, 2023). "The manifestation of FSGS alone is common in individuals with pathogenic INF2, but only one case of CMT has been described to date that makes the absence of accompanying renal disease explicit." (PMID 34685534, 2021).
peripheral neuropathy (5 papers, 2018 to 2025). A disorder affecting the peripheral nervous system. "We here report new aspects of peripheral neuropathy in two unrelated CMT-DIE patients caused by INF2 variants and discuss the underlying mechanisms." (PMID 39857711, 2025). "Inverted formin 2 (INF2) regulates actin polymerization and mutations in INF2 were reported to cause SRNS in adolescence and early adulthood, as well as in patients with Charcot–Marie–Tooth disease (characterized by peripheral neuropathy and FSGS on renal biopsy)." (PMID 29594119, 2018). "However, unlike other mitochondrial fission proteins linked to peripheral neuropathy, the impairment of INF2 may actually increase fission." (PMID 33810506, 2021).
infection (4 papers, 2015 to 2024). The state of being infected such as from the introduction of a foreign agent such as serum, vaccine, antigenic substance or organism. "None of the cats showed any clinical signs of the disease throughout the study, with the exception of INF2 (infected by oral route), which had diarrhea on the second day post-infection." (PMID 35243589, 2022). "In the second infection window (stages 79 to 89), the model calculates two infection rates on ripening berries: one for conidial infection (INF2) and another for berry-to-berry infection (INF3)." (PMID 26457808, 2015). "To confirm our results, we also examined infection by microscopy after depletion of FHOD1, FMNL3, GRID2IP or INF2; all four decreased bacterial uptake, though depletion of FMNL3 had the weakest effect." (PMID 27152864, 2016). "Contrary to expectations, the animal infected by means of spraying (INF1) tested positive as regards the rectal swab on the three first days after infection, while the animal infected by the oral route (licking infection model, INF2) tested negative as regards the rectal swab in all the samplings." (PMID 35243589, 2022).
neurological disease (4 papers, 2014 to 2025). "In INF2—a formin linked to inherited renal and neurological disease in humans—the DID is preceded by a short N-terminal extension of unknown structure and function." (PMID 36306014, 2022). "Inverted formin-2 (INF2), a formin linked to inherited renal and neurological disorders, exhibits pathogenic variants that lead to deregulated actin polymerization and nuclear aberrations, ultimately compromising cell viability." (PMID 40993919, 2025). "Future research should focus on identifying the detailed mechanisms of INF2 regulation and its pathogenic variants, exploring potential therapeutic strategies, and understanding the broader implications of INF2 activity in glomerular and neurological diseases." (PMID 39586895, 2024).
cardiac diseases (1 paper, 2024). "Understanding INF2's role in mitochondrial dynamics provides valuable insights into the molecular mechanisms underlying cardiac pathologies and opens new therapeutic avenues for treating heart diseases, emphasizing its potential as a novel target for cardiac therapeutics." (PMID 38464839, 2024). "Consider the potential of targeting DNA-PKcs and INF2 for therapeutic interventions, the implications for patient care in cases of SIC, and how these findings might pave the way for new approaches in mitigating mitochondrial dysfunction in cardiac diseases." (PMID 38464839, 2024).
immune disorder (1 paper, 2017). "As regards to the non-syndromic forms, some are related to a still not completely understood underlying immune disorder, while an increasing number is found to be caused by mutations in genes highly expressed in podocytes (e.g. NPHS1, NPHS2, CD2AP, PLCE1, ACTN4, TRPC6, and INF2)." (PMID 28298181, 2017).
INF2 also shares sentences with these, for which no sentence is quoted: ischemia (2 papers); neurodegenerative disease (2); atypical hemolytic-uremic syndrome (1); Azoospermia (1); chronic inflammatory demyelinating polyradiculoneuropathy (1); colorectal adenocarcinoma (1); deafness (1); Fabry disease (1); gastric cancer (1); genetic disease (1); head and neck cancer (1); hearing loss (1); Klinefelter syndrome (1); liver cancer (1); lung adenocarcinoma (1); melanoma (1); Methylmalonic aciduria (1); nail-patella-like renal disease (1); nephritis (1); nephrosis (1); Oral leukoplakia (1); oral squamous cell carcinoma (1); ovarian carcinoma (1); Pan (1); primary ovarian insufficiency (1); sarcoma (1); schizophrenia (1); Sensory neuropathy (1); Sepsis (1); steroid-resistant nephrotic syndrome (1).
A further 3 diseases each share a sentence with INF2 in 1 paper.